RHOJ (ras homolog family member J)
Diseases named in the same sentence as RHOJ in open-access papers (continued):
Sharing a sentence is not in itself a finding about the gene and the disease.
tumor (continued). "RhoJ has also been shown to be expressed in endothelial cells and plays an important role in regulating endothelial cell migration and tumor angiogenesis." (PMID 35173528, 2022). "The small Rho GTPase RhoJ is abundantly expressed in endothelial cells during tumor progression, and its role in angiogenesis has been extensively reported 38-40." (PMID 35173528, 2022). "Consistently, a hybrid radiosensitizing nanoparticle functionalized by an anti-RhoJ antibody selectively inhibited tumor angiogenesis upon a low dosage of radiation." (PMID 33916163, 2021). "The potential of RhoJ as an anti-tumor target is further supported by its expression in tumor cells per se, such as melanoma, gastric cancer, glioblastoma multiforme, and breast cancer." (PMID 33916163, 2021). "Consistently, when the mice were sacrificed it was discovered that tumor weight was significantly smaller in mice receiving the inoculation of RhoJ-depleted cells than the control cells." (PMID 32984327, 2020). "RhoJ also regulates tip cell biology, but is instead required for tip cell selection, as KO of RhoJ reduces the number of tip cells in angiogenic tumor vessels in addition to reduced vessel continuity." (PMID 31174284, 2019). "RhoJ is highly expressed in tumor vasculature and regulates both new vessel growth and formed vessel integrity." (PMID 31174284, 2019). "Therapies targeting Rho GTPases have great potential to inhibit angiogenesis-dependent tumor growth, especially when considering the high level of enrichment of some Rho GTPases including RhoB and RhoJ in diseased vessels." (PMID 31174284, 2019). "It is also interesting to find RHOJ that is known to be enriched in tumor endothelial cells and to be involved in their motility and in tumor progression, and it is also considered a selective antiangiogenic target." (PMID 29349517, 2018). "In order to better understand how RhoJ promotes tumor growth, the whole genome expression profiles of BrafV600E;Ptenfl/+;RhoJ+/+ tumors and BrafV600E;Ptenfl/+;RhoJ-/- tumors were examined (complete list in S1 Dataset)." (PMID 28753606, 2017). "A systematic review was related to “small Rho GTPase” or “RhoJ” with “endothelial motility, tube formation and focal adhesion” and “tumor therapy”." (PMID 27556037, 2016). "This study demonstrates a role for RhoJ in regulating tumour angiogenesis and in mediating focal adhesion dynamics through its association with the GIT–PIX complex." (PMID 24928894, 2014). "RhoJ is a Rho GTPase expressed in endothelial cells and tumour cells, which regulates cell motility, invasion, endothelial tube formation and focal adhesion numbers." (PMID 24928894, 2014). "Consistent with its role in endothelial tube formation in vitro, are our observations that knockout of RhoJ results in diminished tumour growth and reduced vessel density." (PMID 24928894, 2014). "RhoJ-knockout mice showed reduced tumour growth and diminished tumour vessel density, identifying a role for RhoJ in mediating tumour angiogenesis." (PMID 24928894, 2014). "Recently RhoJ has been identified as part of a tumour angiogenesis signature – one of 20 genes highly upregulated in tumour vessels." (PMID 24928894, 2014). "Knockout of RhoJ reduced the growth and vascularisation of subcutaneous tumours compared with wild-type controls." (PMID 24928894, 2014). "RhoJ deficiency results in impaired VEGF-induced endothelial cell migration, impaired retinal vascular angiogenesis early during development, and impaired tumor angiogenesis." (PMID 40950721, 2025). "Researchers used elegant in vitro and in vivo mouse models to demonstrate that RHOJ is highly expressed in EMT tumor cells and modulates resistance to different chemotherapies, but further studies are still needed to validate their findings in clinical samples from patients with skin SCCs." (PMID 37779170, 2023).
tumor (continued). "However, the development of an effective and safe RHOJ inhibitor remains a challengeable task, and further in-depth studies are needed to discovery strategies to specifically block tumor progression with minimal side effects in healthy tissue." (PMID 37779170, 2023). "Since RhoJ, a small GTPase of the Cdc42 subfamily, has been involved in tumor-induced angiogenesis and the metastatic dissemination of cancer cells, we hypothesized that it might be a target of oncogenic Gαq signaling via PDZ-RhoGEF." (PMID 37958718, 2023). "Next, we assessed whether RHOJ overexpression can confer resistance to chemotherapy in sensitive epithelial tumour cells." (PMID 36949199, 2023). "However, only EMT tumour cells activate dormant origins in a RHOJ-dependent manner, which facilitates continued DNA replication despite the slowdown of replication forks and promotes cell survival after chemotherapy." (PMID 36949199, 2023). "However, phosphorylation of histone 2A.X at Ser 139 (γ-H2AX) was significantly increased after chemotherapy in RHOJ-KO EMT tumor cells compared with WT EMT tumor cells, suggesting that RHOJ prevents DNA damage accumulation in EMT tumor cells." (PMID 37779170, 2023). "In addition, RHOJ interruption has been reported as an effective therapeutic option for targeting the tumor vascular system 25-27." (PMID 37781036, 2023). "Likewise, in vivo, compared to the control group, the subcutaneous xenograft model of NCG mice showed smaller tumor volume, slower growth rate, and lighter tumor weight in the RHOJ knockdown group (SGC7901, SNU-1)." (PMID 37781036, 2023). "In addition, a higher percentage of origin firing was observed in RHOJ expressed tumor cells after chemotherapy, demonstrating that RHOJ promoted DNA replication by activating new origins of replication in EMT tumor cells during chemotherapy." (PMID 37779170, 2023). "Nevertheless, the expression and function of RhoJ in tumor angiogenesis remain uncertain." (PMID 37762382, 2023). "Using genome-wide transcriptomic and proteomic profiling, we found that RHOJ regulates EMT-associated resistance to chemotherapy by enhancing the response to replicative stress and activating the DNA-damage response, enabling tumour cells to rapidly repair DNA lesions induced by chemotherapy." (PMID 36949199, 2023). "These genes were primarily linked with the organization of extracellular matrix and binding of platelet-derived growth factor, suggesting a probable mechanism through which RHOJ could affect the tumor microenvironment and carcinogenesis." (PMID 37762382, 2023). "This implies that RHOJ could play a role in regulating tumor–immune system interactions, thereby possibly contributing to immune evasion, a trait frequently observed in aggressive cancers." (PMID 37762382, 2023). "This implies that urothelial tumors with high RHOJ expression may display an increased immune response in the tumor microenvironment." (PMID 37762382, 2023). "Higher activation of CDKs, including CDK1 and CDK4, was observed in EPCAM− tumour cells compared with in EPCAM+ and Rhoj-KO EPCAM− cells after chemotherapy suggesting that RHOJ enables EMT tumour cells to progress in the cell cycle and continue DNA synthesis after chemotherapy." (PMID 36949199, 2023). "CDC42 and RHOJ are both known to have specific roles in tumor angiogenesis." (PMID 35385746, 2022). "Similarly, KO of RhoJ increases tumor vessel permeability, suggesting a normal requirement for RhoJ in stabilizing vessel junctions." (PMID 31174284, 2019). "Indeed, RhoJ KO mice experience reduced Lewis Lung carcinoma and breast tumor growth and metastasis that is correlated with decreased tumor blood vessel density." (PMID 31174284, 2019). "There was a significant delay in tumor progression in RhoJ KO mice as compared to RhoJ WT mice." (PMID 28753606, 2017).
tumor (continued). "Finally, administering FRAX597 after tumors were visible also affected tumor growth, suggesting that PAK and RhoJ modulate both the phases of tumor initiation and tumor progression." (PMID 28753606, 2017). "Future studies will address whether RhoJ has independent effects on tumor initiation and metastasis." (PMID 28753606, 2017). "RHOJ belongs to the Rho GTPase subfamily expressed mainly in endothelial and tumor cells." (PMID 28727754, 2017). "Additionally, we further shed light on the fact that RhoJ was a selective and effective therapeutic target in tumor tissues or retinopathy." (PMID 27556037, 2016). "More research is necessary to understand the role of RhoJ in many aspects, on the basis of current knowledge of the role of RhoJ blockade in tumor vessels, there are opportunities for the therapy of tumor, and RhoJ is expressed outside tumour vasculature and is involved in wound healing." (PMID 27556037, 2016). "We also show that RhoJ plays a role in tumour angiogenesis in vivo." (PMID 24928894, 2014). "The rapid growth of tumours is crucially dependent on the development of vessels to sustain the tumour cell proliferation, and our data would suggest that RhoJ is required to facilitate this process." (PMID 24928894, 2014). "Understanding the biology of RhoJ might provide therapeutic opportunities in targeting both tumour cells and the tumour vasculature." (PMID 24928894, 2014). "Additionally, RHOJ may limit immune cell infiltration into the tumor core and promote immune evasion by contributing to vascular abnormalities and impaired barrier function." (PMID 41548474, 2026). "They found that RHOJ regulates drug resistance associated with EMT by a response enhancement to replicative stress, along with the activation of DNA damage response, thus enabling the tumor cells to quickly repair any DNA damage caused by the chemotherapeutic agents." (PMID 39200265, 2024). "To determine whether RHOJ inhibits EMT tumour cells apoptosis by promoting DNA repair and/or replicative tolerance to damaged DNA, as suggested by the proteomic data, we first investigated the level of histone 2A.X phosphorylated at Ser139 (γ-H2AX), a mark of DNA damage after chemotherapy." (PMID 36949199, 2023). "The following problems remain to be further studied whether RHOJ-mediated signaling devotes to developing anti-tumor immunity in GC cells and whether the combination of small molecule compounds targeting RHOJ and immunosuppressants can improve the prognosis of GC patients." (PMID 37781036, 2023). "In our risk model, the expression of five genes (PODN, NPY, MICU3, TUBB6 and RHOJ) was decreased in tumor tissues, and the greater the degree of downregulation was, the better the prognosis was, indicating that the hypermethylation of these genes may play a protective role in GC patients." (PMID 32174791, 2020). "While the effects of RhoJ deletion on lung metastasis was dramatic, it was difficult to examine whether this phenotype was a consequence of a direct effect of RhoJ on lung metastasis or simply a consequence of the fact that RhoJ knockout mice had a lower tumor burden than RhoJ wild type mice at p30." (PMID 28753606, 2017). "Using transfection of nuclear actin chromobody in different tumor cells, researchers found an increase in nuclear actin filament in EPCAM− cells compared to that in EPCAM+ and RHOJ-KO EPCAM−cells, suggesting that RHOJ modulates nuclear actin polymerization." (PMID 37779170, 2023). "Here, we have presented additional effortsof our drug discoveryprogram targeting the CDC42 GTPase (RHOJ, CDC42, and RHOQ) proteins,which are overexpressed in multiple tumor types." (PMID 37026468, 2023). "CDC42 GTPases (RHOJ,CDC42, and RHOQ) are overexpressed in multipletumor types and activate pathways critical for tumor growth, angiogenesis,and metastasis." (PMID 37026468, 2023).
tumor (continued). "In conclusion, our study identified the key role of RHOJ and the mechanisms by which RHOJ promotes resistance to chemotherapy in EMT tumour cells, with important implications for the development of new strategies to overcome resistance to anticancer therapy." (PMID 36949199, 2023). "To define mechanistically how RHOJ promotes resistance to therapy in EMT tumour cells, we first performed bulk RNA-sequencing (RNA-seq) analysis of shRNA control and Rhoj-KD EPCAM− tumour cells." (PMID 36949199, 2023). "To better understand how RhoJ and PAK regulate tumor formation, we examined how RhoJ deletion affected gene expression in transformed melanocytes." (PMID 28753606, 2017). "Future studies will examine how RhoJ cooperates with other MAPK drivers, such as NRAS, to promote tumor growth." (PMID 28753606, 2017). "Genes such as INHBA, IGF2, LGALS1, RHOJ, and THBS2 were upregulated in the tumor buds but downregulated in the microenvironment." (PMID 28687755, 2017). "To determine whether RHOJ also mediates EMT resistance to therapy in vivo, we generated Rhoj conditional knockout (Rhoj KO) tumours using Lgr5creERKrasG12Dp53cKORhojcKORosa-YFP mice." (PMID 36949199, 2023). "Although the amplification of tumor volume was not altered by RhoJ knockdown at earlier points (15 and 20 days) following the inoculation, it was significantly slowed toward the end (25 and 30 days)." (PMID 32984327, 2020). "RhoJ is an endothelial cell-restricted Rho GTPase that mediates vascular morphogenesis and is regulated by the transcription factor, ERG26, and is an effective and selective target for tumor angiogenesis and vascular disruption." (PMID 30718678, 2019). "Additionally, it was observed that knockdown of RHOJ resulted in decreased tumor cell proliferation and migration, while having no impact on the expression of EMT markers." (PMID 37779170, 2023). "To study the effect of RhoJ on GBM angiogenesis and growth in vivo, we subcutaneously injected U87 cells infected by plenti-RhoJ or plenti-con in NOD-SCID mice and found that the tumor tissues in plenti-RhoJ group grew faster, larger and heavier, compared with those in plenti-con group." (PMID 35173528, 2022). "At present, there is no relevant report on RhoJ in tumor immunity." (PMID 35173528, 2022). "All these data indicated that RhoJ could promote GBM angiogenesis and tumor growth in vivo." (PMID 35173528, 2022). "In contrast, the studies presented here define a role for RhoJ signaling in regulating the growth of BRAF mutant melanocytes at all stages, and result in the remarkable observation that early, limited treatment with PAK inhibitors is effective in halting tumor growth." (PMID 28753606, 2017). "In this study, we were unable to examine whether RhoJ had an independent effect on tumor metastasis as we had no method to compare the number of metastasis in mice that had the same tumor burden." (PMID 28753606, 2017). "In addition, blood vessels in tumor tissues were labeled with CD31 in the sections of metastatic lung foci from NCG mice, and the results confirmed that the number and density of angiogenesis in the RHOJ knockdown group were lower than that in the control group." (PMID 37781036, 2023). "In the TCGA BLCA database, high RHOJ expression showed a positive correlation with macrophages (r = 0.21), monocytes (r = 0.20), natural killer cells (r = 0.14), and T cells (r = 0.28), while displaying a negative correlation with tumor cell proliferation (r = −0.13)." (PMID 37762382, 2023). "EPCAM+, EPCAM− and EPCAM−Rhoj-KO tumour cells similarly increased the level of phosphorylated ATM/ATR substrates after cisplatin/5FU administration, showing that RHOJ does not control ATM and ATR activation after chemotherapy." (PMID 36949199, 2023).
tumor (continued). "RhoJ deletion significantly inhibited the growth of melanoma tumors that expressed either no PTEN (p<0.0001, Log-rank) or had one functional copy of PTEN (p<0.0001, Log-rank), suggesting that RhoJ drives tumor growth by amplifying BRAF and not AKT signaling." (PMID 28753606, 2017).
cancer (17 papers, 2013 to 2025). A tumor composed of atypical neoplastic, often pleomorphic cells that invade other tissues. "This paradoxical observation requires further investigation, given that RHOJ has previously been linked to promoting cell proliferation and survival in other forms of cancer." (PMID 37762382, 2023). "RHOJ was previously reported to be associated with cancer metastasis." (PMID 39984455, 2025). "Using gain and loss of function studies in vitro and in vivo, we found that RHOJ—a small GTPase that is preferentially expressed in EMT cancer cells—controls resistance to therapy." (PMID 36949199, 2023). "RHO GTPases, for instance RHOJ, serve as crucial controllers of cell motility and can also contribute to cancer progression by encouraging cell migration and invasion." (PMID 37762382, 2023). "RHOJ has been reported to regulate cytoskeletal dynamics, which is a crucial process in cell migration and invasion, thereby contributing to the metastatic potential of cancer cells." (PMID 37762382, 2023). "Our data are similar to that recently reported; they demonstrate that a variety of anti-cancer agents are more effective in RhoJ-knockout mice, suggesting that inhibition of RhoJ signalling might have therapeutic benefit." (PMID 24928894, 2014). "Blockade of RhoJ may be a therapeutic direction for cancer and cardiovascular disease treatment." (PMID 35173528, 2022). "Here, we focus on CDC42 and RHOJ, two of the three CDC42 family members (CDC42, RHOJ, and RHOQ) that have the most defined roles in cancer." (PMID 35385746, 2022). "Of these genes, RHOJ and FSTL1 have particularly been characterized more extensively, whereas ETV1 and HAS2 are newly emerging in the cancer literature." (PMID 31109321, 2019). "Out of 52 genes investigated, we observed that many genes upregulated in M2 and downregulated in M1 macrophages–ACTN1, FLRT2, MRC1, PTGS1, RHOJ, TMEM158–correlated positively with the EMT scores (first 6 rows) across multiple cancer types." (PMID 30729096, 2019). "Recent studies have suggested that RHOJ is preferentially expressed in epithelial-to-mesenchymal transition cells, with interaction with proteins (FLNB, TLN1 and IPO9) that regulate nuclear actin and inhibit actin polymerization in cancer cells." (PMID 39984455, 2025). "We observed that ARN22089 could inhibit RHOJ/PAK interactions at an approximate EC50 between 1 and 5 μM, consistent with the IC50s observed in the cancer cell lines tested." (PMID 35385746, 2022). "The expression of RhoJ was not reported in EMBL-EBI but a low level was documented in most cancer cell lines in the CCLE database." (PMID 34405015, 2021).
infection (3 papers, 2014 to 2023). The state of being infected such as from the introduction of a foreign agent such as serum, vaccine, antigenic substance or organism. "On this basis, we established stable RHOJ knockdown and RHOJ overexpression GC cells line (SGC7901, SNU-1, and MKN-45) by infection with lentiviral vectors respectively." (PMID 37781036, 2023).
adenocarcinoma (1 paper, 2015). A common cancer characterized by the presence of malignant glandular cells. "For adenocarcinoma specifically, DM was observed in promoters [hypermethylated RASL12; SPTAN1, mir-26a, hypomethylated NQO1, SIRPB1, NF1A] and gene bodies [hypermethylated AKAP13, ANK family, PRKCE, ROS1; hypomethylated FAM171A1, PARK2, BCAS3, RHOJ] and many others." (PMID 26683690, 2015).
RHOJ also shares sentences with these, for which no sentence is quoted: cardiovascular disease (2 papers); atherosclerosis (1); breast tumor (1); colorectal cancer (1); diabetic kidney disease (1); endothelial dysfunction (1); lung carcinoma (1); lymphoma (1); metastatic melanoma (1); osteoporosis (1); retinopathy (1); skin squamous cell carcinoma (1); urothelial carcinoma (1); vitiligo (1).